FNDC3B (fibronectin type III domain containing 3B)
Description:
May be a positive regulator of adipogenesis.
Synonyms: FAD104; DKFZp762K137; FLJ23399; PRO4979; YVTM2421
Tractability: Antibody: UniProt predicts a signal peptide or a membrane-spanning region. PROTAC: ubiquitination databases record sites on it; its protein half-life has been measured.
Gene: Protein-coding gene on chromosome 3 (172,039,547 to 172,405,418, forward strand). Ensembl gene ENSG00000075420.
Subcellular location: Membrane
Subcellular location (Human Protein Atlas): Endoplasmic reticulum
Gene Ontology:
Molecular function: RNA binding
Cellular component: cytoplasm; endomembrane system; membrane
Genetic constraint (gnomAD): Loss-of-function variants: 11 observed, 110.93 expected, observed/expected ratio (o/e) 0.0992, 90% interval 0.061 to 0.16. The upper end of that interval is the gene's LOEUF score, 0.16, which puts it in group 1 of 6, group 1 being the genes least tolerant of losing a copy. Missense variants: 1,030 observed, 1,305.3 expected, observed/expected ratio (o/e) 0.79, 90% interval 0.75 to 0.83. Synonymous variants: 461 observed, 491.11 expected, observed/expected ratio (o/e) 0.94, 90% interval 0.87 to 1.01.
Homologues: Orthologues: chimpanzee FNDC3B (99% identical), macaque FNDC3B (98% identical), rabbit FNDC3B (97% identical), dog FNDC3B (96% identical), pig FNDC3B (94% identical), rat Fndc3b (93% identical), mouse Fndc3b (93% identical), guinea pig FNDC3B (87% identical), tropical clawed frog fndc3b (73% identical), zebrafish fndc3ba (69% identical), zebrafish fndc3bb (54% identical), Drosophila melanogaster mtgo (34% identical), and 1 more. Paralogues in human: FNDC3A (51% identical), MYOM1 (18% identical), MYOM2 (17% identical), MYOM3 (16% identical), MYBPC3 (15% identical), MYBPC1 (14% identical), MYBPC2 (14% identical), IGSF22 (13% identical), OBSL1 (13% identical), MYBPH (6% identical), MYBPHL (5% identical).
Diseases named in the same sentence as FNDC3B in open-access papers:
FNDC3B is named in the same sentence as 75 diseases in open-access papers, as found by Europe PMC text mining. Sharing a sentence is not in itself a finding about the gene and the disease. The quoted sentences say what the papers report.
hepatocellular carcinoma (19 papers, 2013 to 2026). A malignant tumor that arises from hepatocytes. "FNDC3B (fibronectin type III domain containing 3B) is highly expressed in hepatocellular carcinoma (HCC) and other cancer types, and fusion genes involving FNDC3B have been identified in HCC and leukemia." (PMID 38403291, 2024). "FNDC3B has also been identified as an oncogene that promotes cell migration in hepatocellular carcinoma." (PMID 38303056, 2024). "FNDC3B (fibronectin type III domain containing 3B) exhibits high expression level in hepatocellular carcinoma (HCC) and other cancers types, and its gene locus, 3q26, is frequently amplified in various cancer genome." (PMID 38403291, 2024). "Recent studies have revealed that FNDC3B plays a crucial role in various cancers, including acute myeloid leukemia, hepatocellular carcinoma, cervical cancer, and colorectal cancer −." (PMID 38802851, 2024). "For instance, overexpression of FNDC3B in hepatocellular carcinoma cell lines enhanced cell migration and invasion, suggesting that FNDC3B behaves like an oncogene and promotes tumor metastasis in hepatocellular carcinoma." (PMID 38137388, 2023). "Recent research has demonstrated that FNDC3B is abnormally expressed in several types of human cancers, including hepatocellular carcinoma, acute myeloid leukemia, colorectal cancer, and cervical cancer." (PMID 38137388, 2023). "The FNDC3B gene is an oncogene in hepatocellular cancer and the high expression of FNDC3B induces the EMT process, PI3K/Akt, Rb1, and TGFβ signaling." (PMID 35625741, 2022). "In recent years, overexpression of FNDC3B and its tumor-promotive roles have been reported in several tumors, such as hepatocellular carcinoma, tongue squamous cell carcinoma, and glioma." (PMID 34603558, 2021). "FNDC3B has a role in cell migration and invasiveness in hepatocellular carcinoma and glioblastoma cells." (PMID 29813068, 2018). "It is reported that miRNA-143 promotes invasion and metastasis of hepatocellular carcinoma and prostate cancer cells by repression of FAD104/FNDC3B expression." (PMID 25671570, 2015). "Notably, previous studies have also suggested the potential utility of FNDC3B as a prognostic biomarker across several cancers including cervical cancer, hepatocellular carcinoma, colorectal cancer and glioblastoma." (PMID 38581008, 2024). "This study proposes that FNDC3B could act as a potential therapeutic target and biomarker for hepatocellular carcinoma metastasis." (PMID 38137388, 2023). "Also, through inhibition of FNDC3B, miR-143 promotes the metastasis of hepatic carcinoma (animal study) to the lung and the metastasis of prostate cancer cells." (PMID 24774218, 2014). "Moreover, it was demonstrated that the up-regulation of miR-143 expression in hepatocellular carcinoma (HCC) promoted cancer cells metastasis by repressing FNDC3B." (PMID 23383988, 2013). "The abnormal expression of FNDC3B is observed in hepatocellular carcinoma (HCC), acute myeloid leukemia (AML), and cervical cancer." (PMID 39273383, 2024). "FNDC3B is an oncogene firstly identified in hepatocellular carcinoma (HCC)." (PMID 34976823, 2021). "FNDC3B is mainly composed of fibronectin III (FNIII) domain, which has been widely reported to be upregulated in cancer as a oncogene, such as hepatocellular carcinoma, oral tongue squamous cell carcinoma and gastric cancer." (PMID 33336045, 2020).
cervical cancer (12 papers, 2017 to 2024). A primary or metastatic malignant neoplasm involving the cervix. "In cervical cancer, FNDC3B can promote the ability of proliferation and metastasis of tumor cells through activating PI3K/mTOR signaling pathway." (PMID 38581008, 2024). "For instance, Han reported that FNDC3B expression was correlated with a worse prognosis in cervical cancer, while its carcinogenic effects are still unclear." (PMID 36275754, 2022). "In recent years, many evidence proved the positive role of FNDC3B in colorectal cancer, cervical cancer, glioblastoma, and tongue squamous cell carcinoma cells." (PMID 35060189, 2022). "For the past few years, emerging evidence has demonstrated that FNDC3B was abnormally expressed in several types of human cancers, including hepatocellular carcinoma, acute myeloid leukemia, colorectal and cervical cancers." (PMID 36275754, 2022). "In cervical cancer, a comprehensive bioinformatic analysis revealed that differential FNDC3B expression could distinguish between different stages of cervical cancer, with high FNDC3B expression indicating a shorter OS and DSS." (PMID 38581008, 2024). "Additionally, activation of PI3K/mTOR signaling pathway mediated by FNDC3B was found to induce invasion and metastasis in cervical cancer." (PMID 38581008, 2024). "The results also revealed that FNDC3B upregulation may be a biomarker for poor prognosis of patients with cervical cancer." (PMID 38137388, 2023). "Furthermore, FNDC3B demonstrated predictive value for cervical cancer progression." (PMID 38581008, 2024). "A publicly available DNA microarray dataset revealed that three of the candidates (PGM1, FNDC3B, and IGF2R) were aberrantly expressed in cervical cancer tissues relative to normal cervix tissues." (PMID 31748500, 2019).
glioblastoma (12 papers, 2018 to 2024). The most malignant astrocytic tumor (WHO grade IV). "FNDC3B was enriched in patients with glioblastoma and caused poor prognosis." (PMID 33336045, 2020). "Furthermore, FNDC3B was highly expressed in glioblastoma, and its high expression was associated with unfavorable prognosis." (PMID 33336045, 2020). "Although FNDC3B is attracting attention as a significant biomarker in other cancer types, its biological function and usefulness as a biomarker in glioblastoma are still unclear." (PMID 38137388, 2023). "Wang and Xu reported that MiR-1225-5p and MiR-129-5p inhibit the malignant glioblastoma cells via targeting FNDC3B." (PMID 36275754, 2022). "In previous studies, it can be found that the RNA binding proteins PTRF and FNDC3B have been identified as potential prognostic biomarkers for glioblastoma." (PMID 33711033, 2021). "Herein, our study is the first to clarify the relationship between FNDC3B and miR-1225-5p in glioblastoma." (PMID 33336045, 2020). "Subsequently, for the first time, we determined that FNDC3B is a downstream target gene of miR-1225-5p, and miR-1225-5p negatively regulated its expression in glioblastoma." (PMID 33336045, 2020). "The findings of this study are restricted to glioblastoma cell lines in vitro, so the function of miR-1225-5p/FNDC3B axis in vivo needs further researches." (PMID 33336045, 2020). "A study of glioblastoma found that expression levels of eight RBP-related genes were strongly associated with tumor prognosis, and identified PTRF and FNDC3B among them as potential prognosis-related biomarkers." (PMID 33195699, 2020). "MiR-1225-5p was an upstream regulatory molecule of FNDC3B, which posttranscriptionally inhibited the expression of FNDC3B in glioblastoma cells." (PMID 33336045, 2020). "Survival analysis revealed eight RBPs (PTRF, FNDC3B, SLC25A43, ZC3H12A, LRRFIP1, HSP90B1, HSPA5, and BNC2) are significantly associated with the survival of glioblastoma patients." (PMID 32272554, 2020). "Taken together, these results illustrated that miR-1225-5p exerted the anticancer function in glioblastoma via regulating FNDC3B." (PMID 33336045, 2020). "Overexpression of FNDC3B prevents the miR-1225-5p-mediated suppression on malignant phenotype of glioblastoma cells." (PMID 33336045, 2020). "Another study suggested that miR-129-5p mediates FNDC3B to suppress proliferation, migration and invasion of glioblastoma cells U87 cells." (PMID 31649488, 2019). "Notably, a few studies have demonstrated that FNDC3B expression levels are correlated with glioblastoma." (PMID 36275754, 2022). "Additionally, studies show that FNDC3B plays an important regulatory role in glioblastoma, and that targeted regulation of FNDC3B can effectively inhibit glioblastoma proliferation and invasion." (PMID 36056336, 2022). "We found that FNDC3B was the downstream target gene of miR-1225-5p, and based on the results of biological functional assays, overexpression of FNDC3B can reverse miR-1225-5p-mediated inhibition in glioblastoma." (PMID 33336045, 2020). "Moreover, based on the analyses of the cancer genome atlas (TCGA), Oncomine and CGGA databases, FNDC3B was enriched in glioblastoma and high expression of FNDC3B led to poor prognosis." (PMID 33336045, 2020). "Based on the literature and the bioinformatics analysis, we designed to affirm the function of miR-1225-5p in glioblastoma and explore whether this function is achieved by regulating FNDC3B, hoping to provide more extensive data support for the clinical application of miR-1225-5p in glioblastoma." (PMID 33336045, 2020). "Also, the characterization of FNDC3B in glioblastoma has also been studied." (PMID 33336045, 2020). "This suggested that FNDC3B may be a prognostic factor for glioblastoma." (PMID 33336045, 2020). "WHO IV glioblastoma showed the highest FNDC3B expression compared with WHO II and WHO III glioblastoma, and the differences were statistically significant." (PMID 33336045, 2020).
glioblastoma (continued). "More importantly, we identified non-canonical RNA-binding proteins PTRF and FNDC3B, showing them to be potential prognostic biomarkers for glioblastoma." (PMID 32272554, 2020). "In addition, we demonstrated that patients with WHO IV glioblastoma showed the highest FNDC3B expression compared with WHO II and WHO III glioblastoma, and the higher the expression, the lower the survival rate." (PMID 33336045, 2020).
glioma (11 papers, 2015 to 2026). A benign or malignant brain and spinal cord tumor that arises from glial cells (astrocytes, oligodendrocytes, ependymal cells). "The overexpression of FNDC3B reported in several types of human cancers, including gliomas, has been associated to a dysregulation of EMT and increased cells proliferation." (PMID 38969910, 2024). "Among 6216 samples from 5774 patients in 14 glioma datasets, the overall alteration frequency of FNDC3B gene is 1.5% (71/4774); amplification, mutations, and deep deletions were the most common types of alteration." (PMID 36275754, 2022). "In multivariate Cox regression analysis, FNDC3B was independently associated with overall survival, suggesting it could be an independent prognostic biomarker for glioma (HR = 1.72; 95% CI = 1.07-2.80; P < 0.05)." (PMID 36275754, 2022). "Moreover, expression of FNDC3B was significantly associated with infiltrating levels of several types of immune cells and most of their gene markers in glioma." (PMID 36275754, 2022). "Moreover, FNDC3B is associated with the infiltration of various immune cells, and it may play a vital role in the tumor immune microenvironment of glioma." (PMID 36275754, 2022). "FNDC3B strongly correlates with immune infiltration in gliomas, modulating above all cytotoxic T cells and antitumor associated immune cells." (PMID 38969910, 2024). "In conclusion, our comprehensive analysis revealed that FNDC3B was upregulated in glioma, while increased FNDC3B expression predicted an unfavorable prognosis." (PMID 36275754, 2022). "Recently, several studies have reported that FNDC3B is an oncogene in various cancers, including glioma." (PMID 36275754, 2022). "In summary, these results suggested that FNDC3B was correlated with clinically relevant immune checkpoint molecules in glioma." (PMID 36275754, 2022). "Until now, there are very limited studies on the correlation between FNDC3B and tumor-infiltrating lymphocytes (TILs) in glioma." (PMID 36275754, 2022). "To further investigate the functions of FNDC3B in glioma, we performed GSEA analysis using DEGs based on TCGA LGG data." (PMID 36275754, 2022). "In human cancer tissues, FNDC3B protein expression in glioma was ranked as the top 12 out of 20 distinct cancer types." (PMID 36275754, 2022). "Based on the integrated machine learning methods, this is the first report to comprehensively analyze FNDC3B expression profiles and its correlation with immune infiltrates in gliomas." (PMID 36275754, 2022). "Our findings revealed that higher FNDC3B expression is closely correlated with the malignant clinical characters of gliomas." (PMID 36275754, 2022). "In this study, we comprehensively investigated the expression, prognostic value, and immune significance of FNDC3B in glioma using several databases and a variety of machine learning algorithms." (PMID 36275754, 2022). "Comparison of FNDC3B across the seven studies showed a Median Rank = 302, suggesting that FNDC3B was highly expressed in glioma tissues and concentrated both in LGG and GBM (P <0.0001)." (PMID 36275754, 2022). "In general, we identified and validated the expression level of FNDC3B as a useful and independent prognostic biomarker for glioma." (PMID 36275754, 2022). "In this study, we identified that FNDC3B was highly expressed in glioma tissues by mining multiple databases, and the expression levels of FNDC3B increased with the level of the malignant degree, which was also confirmed in another study." (PMID 36275754, 2022). "Among them, 11 studies indicated the upregulation of FNDC3B and four studies the downregulation in brain and CNS cancers." (PMID 36275754, 2022). "Firstly, qPCR was utilized for determining the levels of LINC00355 and FNDC3B in glioma cells after their miR-1225 was depleted or overexpressed." (PMID 34603558, 2021).
glioma (continued). "In this study, we analyzed TCGA datasets to study the clinical significance of FNDC3B in glioma patients, finding that higher levels of FNDC3B predicted poorer clinical prognosis." (PMID 34603558, 2021). "CCK-8 assays demonstrated that depression of FNDC3B by si-FNDC3B#3 inhibited the cell proliferation of glioma cells, while reintroduction of LINC00355 was able to reverse the cell proliferation which was suppressed by si-FNDC3B#3." (PMID 34603558, 2021). "In our study, we found that FNDC3B not only acts as a prognostic biomarker, but can also promote glioma cell proliferation." (PMID 32272554, 2020). "Moreover, bioinformatic analysis indicated FNDC3B as a promising prognostic and immunotherapeutic biomarker in glioma and a target of several miRNAs." (PMID 38581008, 2024). "We also investigated the correlations between FNDC3B expression and tumor immune microenvironment (TIM) in LGG patients in order to elucidate the underlying mechanisms and improve molecular diagnosis for glioma patients." (PMID 36275754, 2022). "Therefore, we reported that FNDC3B is a possible prognostic biomarker and an immune-related therapeutic target for glioma, which will be useful for clinical applications." (PMID 36275754, 2022). "Furthermore, a newly integrated analysis of RNA binding proteins in glioma revealed that FNDC3B can not only serve as a useful prognostic biomarker but also promote glioma cell proliferation." (PMID 36275754, 2022). "To evaluate whether FNDC3B expression can predict clinical prognosis of glioma, we constructed a clinical nomogram to estimate long-term survival probabilities." (PMID 36275754, 2022). "Furthermore, univariate and multivariate Cox analysis demonstrated a positive correlation between FNDC3B expression and poor prognosis of patients with glioma." (PMID 36275754, 2022). "Higher FNDC3B expression displayed a remarkably worse overall survival and the expression level of FNDC3B was an independent prognostic indicator for patients with glioma." (PMID 36275754, 2022). "Genetic alterations of FNDC3B in glioma patients were examined using cBioPortal." (PMID 36275754, 2022). "Recent discoveries have revealed that fibronectin type III domain containing 3B (FNDC3B) acts as an oncogene in various cancers; however, its role in glioma remains unclear." (PMID 36275754, 2022). "The immunohistochemistry result revealed upregulated FNDC3B in glioma samples." (PMID 36275754, 2022). "This study demonstrated that FNDC3B may be involved in the occurrence and development of glioma and can be regarded as a promising prognostic and immunotherapeutic biomarker for the treatment of glioma." (PMID 36275754, 2022). "In addition, FNDC3B, a membrane protein, not only promotes migration and invasion of glioma cells, but can also act as a prognostic biomarker." (PMID 34733320, 2021). "Data from TCGA datasets revealed that FNDC3B levels were increased in glioma specimens." (PMID 34603558, 2021). "Similar results from wound healing assays were also observed that LINC00355 overexpression could restore the suppressive impacts of si-FNDC3B#3 on glioma cell migration." (PMID 34603558, 2021). "However, there is limited evidence about the exact molecular mechanism involved in FNDC3B-mediated glioma progression." (PMID 34603558, 2021). "Second, more investigations are needed to identify the expression and function of FNDC3B as well as their correlations with immune cell infiltration; thus, further clinical and experimental studies in the laboratory are required for verifying its role in glioma." (PMID 36275754, 2022). "The FNDC3B expression was positively correlated with genes of immune checkpoints, suggesting that FNDC3B could be a regulatory factor of various immune checkpoints in glioma." (PMID 36275754, 2022). "This suggested that FNDC3B may be involved in the regulation of T cell response in glioma." (PMID 36275754, 2022).